FYTTD1 (forty-two-three domain containing 1)
Description:
Required for mRNA export from the nucleus to the cytoplasm. Acts as an adapter that uses the DDX39B/UAP56-NFX1 pathway to ensure efficient mRNA export and delivering to the nuclear pore. Associates with spliced and unspliced mRNAs simultaneously with ALYREF/THOC4.
Synonyms: UIF; DKFZp761B1514
Tractability: PROTAC: UniProt records ubiquitination sites on it; ubiquitination databases record sites on it; its protein half-life has been measured.
Gene: Protein-coding gene on chromosome 3 (197,737,179 to 197,787,596, forward strand). Ensembl gene ENSG00000122068.
Subcellular location: Nucleus, nucleoplasm; Nucleus speckle
Subcellular location (Human Protein Atlas): Nuclear speckles; Nucleoplasm; Cytosol; Nucleoli
Pathways (Reactome):
Metabolism of RNA: Transport of Mature mRNA derived from an Intron-Containing Transcript; mRNA 3'-end processing
Gene Ontology:
Molecular function: mRNA binding; protein binding; RNA binding
Biological process: mRNA export from nucleus
Cellular component: nuclear speck; nucleoplasm; transcription export complex
Genetic constraint (gnomAD): Loss-of-function variants: 8 observed, 17.1 expected, observed/expected ratio (o/e) 0.47, 90% interval 0.27 to 0.84. The upper end of that interval is the gene's LOEUF score, 0.84, which puts it in group 3 of 6, group 1 being the genes least tolerant of losing a copy. Missense variants: 178 observed, 196.62 expected, observed/expected ratio (o/e) 0.91, 90% interval 0.8 to 1.02. Synonymous variants: 78 observed, 74.33 expected, observed/expected ratio (o/e) 1.05, 90% interval 0.87 to 1.27.
Homologues: Orthologues: chimpanzee FYTTD1 (100% identical), macaque FYTTD1 (98% identical), rabbit FYTTD1 (93% identical), mouse Fyttd1 (92% identical), pig FYTTD1 (86% identical), dog FYTTD1 (85% identical), rat Fyttd1 (83% identical), guinea pig FYTTD1 (69% identical), tropical clawed frog fyttd1 (42% identical).
Diseases named in the same sentence as FYTTD1 in open-access papers:
FYTTD1 is named in the same sentence as 1 disease in open-access papers, as found by Europe PMC text mining. Sharing a sentence is not in itself a finding about the gene and the disease. The quoted sentences say what the papers report.
lung carcinoma (1 paper, 2025). "Given the interplay between mRNA export and autophagy, the interaction of TRIM27, FYTTD1, SHISA9 and pack‐years of smoking may influence autophagy and, in turn, affect lung cancer prognosis." (PMID 39630602, 2025).